RN7SL670P (RNA, 7SL, cytoplasmic 670, pseudogene)
Gene: Miscellaneous RNA gene on chromosome 2 (203,259,604 to 203,259,897, forward strand). Ensembl gene ENSG00000264041.
Homologues: Orthologues: chimpanzee Metazoa_SRP (99% identical). Paralogues in human: Metazoa_SRP (75% identical), Metazoa_SRP (72% identical), RN7SL405P (70% identical), Metazoa_SRP (67% identical), Metazoa_SRP (65% identical), Metazoa_SRP (62% identical), Metazoa_SRP (56% identical), Metazoa_SRP (53% identical), Metazoa_SRP (51% identical), Metazoa_SRP (50% identical), Metazoa_SRP (49% identical), Metazoa_SRP (48% identical), and 700 more.